LRRC75B (leucine rich repeat containing 75B)
Description:
May suppress myogenic differentiation by modulating MYOG expression and Erk1/2 signaling.
Synonyms: C22orf36; FAM211B; MGC131773
Tractability: No criterion of Open Targets' tractability assessment is met for any kind of drug.
Gene: Protein-coding gene on chromosome 22 (24,585,620 to 24,593,208, reverse strand). Ensembl gene ENSG00000178026.
Subcellular location (Human Protein Atlas): Cytosol; Nucleoplasm
Genetic constraint (gnomAD): Loss-of-function variants: 12 observed, 10.9 expected, observed/expected ratio (o/e) 1.1, 90% interval 0.7 to 1.73. The upper end of that interval is the gene's LOEUF score, 1.73, which puts it in group 6 of 6, group 1 being the genes least tolerant of losing a copy. Missense variants: 344 observed, 354.62 expected, observed/expected ratio (o/e) 0.97, 90% interval 0.89 to 1.06. Synonymous variants: 178 observed, 167.01 expected, observed/expected ratio (o/e) 1.07, 90% interval 0.94 to 1.21.
Homologues: Orthologues: chimpanzee LRRC75B (99% identical), macaque LRRC75B (93% identical), dog LRRC75B (85% identical), pig LRRC75B (82% identical), rat Lrrc75b (81% identical), mouse Lrrc75b (81% identical), guinea pig LRRC75B (76% identical).
Diseases named in the same sentence as LRRC75B in open-access papers:
LRRC75B is named in the same sentence as 1 disease in open-access papers, as found by Europe PMC text mining. Sharing a sentence is not in itself a finding about the gene and the disease.
LRRC75B shares sentences with these, for which no sentence is quoted: cancer (1 paper).